RAD9A (RAD9 checkpoint clamp component A)
Diseases named in the same sentence as RAD9A in open-access papers:
RAD9A is named in the same sentence as 31 diseases in open-access papers, as found by Europe PMC text mining. Sharing a sentence is not in itself a finding about the gene and the disease. The quoted sentences say what the papers report.
prostate carcinoma (12 papers, 2011 to 2023). A carcinoma that arises from epithelial cells of the prostate gland. "The results of GEPIA revealed that the RAD9A expression levels were significantly upregulated in the vast majority of cancers including prostate cancer." (PMID 33575255, 2020). "More importantly, apart from functioning as a part of the RAD9A-HUS1-RAD1 complex, RAD9A independently drives prostate cancer metastasis by controlling AGR2 abundance." (PMID 33575255, 2020). "The expression of the AGR2 protein in the prostate cancer cell line PC-3 was shown to be controlled by RAD9A through its specific binding to the 5ʹ-untranslated region of AGR2, and the knockdown of RAD9A resulted in the downregulation of AGR2." (PMID 31247903, 2019). "In fact, the ability of DU145 human prostate cancer cells to develop tumors into nude mice is eliminated with Rad9A knockdown, and the in vitro proliferation of MCF-7 breast cancer cells is inhibited with Rad9A silencing." (PMID 26658951, 2015). "RAD9A overexpression has been observed in a variety of tumors, including breast, lung, thyroid, and prostate cancer." (PMID 21991345, 2011). "RAD9A expression level with clinical features in prostate cancer TMA." (PMID 33575255, 2020). "At the mRNA level, RAD9A were significantly upregulated in many cancers including prostate cancer." (PMID 33575255, 2020). "RAD9A and NIPSNAP1 were among the top increased genes, and RAD9A was correlated with poor prognosis in prostate cancer." (PMID 35327549, 2022).
breast carcinoma (7 papers, 2008 to 2023). "It indicates that the doxorubicin induces the dysregulation of hiPSC-CMs derived RAD9A, HSPA1B, GATA2, IGF2R, CD200, ERCC8, and BCL11A genes that are associated with the pathogenesis of doxorubicin-induced cardiotoxicity in breast cancer patients." (PMID 37684436, 2023). "Rad9A levels are increased in prostate and breast cancer cells." (PMID 26658951, 2015). "Finally, we validated the expression level of immune-related genes in breast cancer patients-derived cardiomyocytes with doxorubicin-induced cardiotoxicity and found that the level of RAD9A, HSPA1B, GATA2, IGF2R, CD200, ERCC8, and BCL11A genes are consistently dysregulated." (PMID 37684436, 2023). "RAD9A has a dual role in cancer (lack of the protein causes cellular sensitivity to DNA damage and in turn provokes cancer, the abundance of the protein due to hypermethylation in intron 2 of the gene leads to advance cancer conditions in prostate and breast cancer)." (PMID 35221838, 2022). "To understand the role of hypermethylation of RAD9A in cancer and oncogenic transformation, we further analyzed BT-549 (breast cancer), MCF7 (breast cancer), EFO-21 (ovary), T47D (breast cancer), and FaDu (squamous cell carcinoma) cell lines." (PMID 35221838, 2022). "Finally, we validated that RAD9A, HSPA1B, GATA2, IGF2R, CD200, ERCC8, and BCL11A genes are consistently dysregulated in the doxorubicin-induced human-induced pluripotent stem cell-derived cardiomyocytes (hiPSC-CMs) derived from breast cancer patients." (PMID 37684436, 2023).
childhood cancer (3 papers, 2011 to 2022). "Collectively, our results support the idea that modulation of RAD9A and other cell cycle arrest and DNA repair proteins contribute to the risk of developing a second malignancy in childhood cancer patients." (PMID 21991345, 2011). "Four childhood cancer patients (1N20, 1N14, 1N07 and 2N21) showed RAD9A epimutations and childhood cancer patient 1N04 showed an elevated RAD9A EMR." (PMID 35221838, 2022). "In conclusion, this is the very first study of RAD9A intron 2 methylation in childhood cancer and Leukemia." (PMID 35221838, 2022). "In the 2C group, the amount of RAD9A protein increased 1.76- and 1.63-fold at 1 h and 4 h, respectively, implying a lower induction (−1.44x, p = 0.012 at 4 h) by DNA damage in childhood cancer patients with a second tumor." (PMID 21991345, 2011). "Since childhood cancer patients and controls enrolled in this study were matched, differences in RAD9A methylation are not be explained by age." (PMID 35221838, 2022).
Fanconi anemia (3 papers, 2011 to 2022). Fanconi anemia (FA) is a hereditary DNA repair disorder characterized by progressive pancytopenia with bone marrow failure, variable congenital malformations and predisposition to develop hematological or solid tumors. "Our assumption of the possible involvement of RAD9A hypermethylation in unknown signaling pathways triggered by hazardous mutations compromised DNA integrity and subsequent tumor formation is further substantiated by analysis of Fanconi anemia fibroblasts." (PMID 35221838, 2022).
infertile (2 papers, 2016 to 2020). "Adult Rad9a-null male mice were infertile as a result of completely blocked spermatogonia differentiation." (PMID 27861152, 2016).
bladder cancer (1 paper, 2023). "The high expression of ABCB9, SPTBN2, GULP1, IGF1, P4HB, NES and DPYSL2 and the low expression of ANXA6, OAS1, RAD9a, DNASE2B and FANCF would be beneficial to the prognosis of bladder cancer patients." (PMID 37845668, 2023).
esophageal cancer (1 paper, 2020). A primary or metastatic malignant neoplasm involving the esophagus. "It is reported that knockdown of RAD9A enhanced esophageal cancer sensitivity to trichostatin A inducing DNA damage." (PMID 33575255, 2020).
Hodgkins lymphoma (1 paper, 2022). A heterogeneous group of malignant lymphoid neoplasms of B-cell origin characterized histologically by the presence of Hodgkin and Reed-Sternberg (HRS) cells in the vast majority of cases. "Four childhood patients with RAD9A EMR >2 % suffered from leukemia (ALL and Hodgkin lymphoma)." (PMID 35221838, 2022).
leukemia (1 paper, 2022). A malignant (clonal) hematologic disorder, involving hematopoietic stem cells and characterized by the presence of primitive or atypical myeloid or lymphoid cells in the bone marrow and the blood. "The other four patients with ≥ 2 % hypermethylated alleles in RAD9A suffered from leukemia." (PMID 35221838, 2022). "To corroborate this finding, we first analyzed RAD9A methylation in the bone marrow of three leukemia patients." (PMID 35221838, 2022). "The involvement of RAD9A hypermethylation in oncogenic transformation is substantiated with experiments performed with bone marrow samples from leukemia patients." (PMID 35221838, 2022). "RAD9A epimutations may have an impact on leukemia and tumorigenesis and can potentially serve as a biomarker." (PMID 35221838, 2022). "Because, there is no research about the involvement of RAD9A hypermethylation, leukemia development and progression to date, we designed experiments with EBV, tumor cell lines, and bone marrow samples from leukemia patients to elucidate a possible mechanistic involvement." (PMID 35221838, 2022).
male infertility (1 paper, 2016). The inability of the male to effect fertilization of an ovum after a specified period of unprotected intercourse. "Rad9a null spermatogonia failed to differentiate into spermatocytes, and testicular cord malformation was observed in mutant mouse testes, which led to complete male infertility." (PMID 27861152, 2016).
retinoblastoma (1 paper, 2022). A malignant tumor that originates in the nuclear layer of the retina. "Patient 1N20, who suffered from sporadic unilateral retinoblastoma, exhibited almost 12 % fully methylated RAD9A alleles in his fibroblasts, indicating that almost one-eighth of his normal cells are endowed with epimutated RAD9A alleles." (PMID 35221838, 2022).
toxoplasmosis (1 paper, 2024). A parasitic disease contracted by the ingestion or fetal transmission of toxoplasma gondii. "The pivotal genes AAMDC, GPR158, RAD9A, STOML1and STRA13 identified in this study have the potential to serve as molecular therapeutic or immunotherapeutic targets for toxoplasmosis; however, their specific function mechanisms require further verification." (PMID 39935538, 2024).
Williams syndrome (1 paper, 2021). "FKBP6 is associated with the Lipin 3 (LPIN3) gene and the RAD9 checkpoint clamp component A (RAD9A) gene and has been associated with Williams syndrome and Williams-Beuren syndrome, but FKBP6 does not have an advantage in terms of the strength of association with the target disease." (PMID 34966851, 2021).
tumor (25 papers, 2008 to 2024). "To test our hypothesis that alterations in tumor-relevant genes may be associated with changes in RAD9A methylation, we performed an SNP array analysis of hypermethylated (4, 6 and 10) and hypomethylated (2 and 9) FaDu subclones." (PMID 35221838, 2022). "Radiation, colony formation assays, cell proliferation, PCR and molecular karyotyping SNP-array experiments using generated FaDu subclones suggest that hypermethylation of RAD9A intron 2 is associated with genomic imbalances in regions with tumor-relevant genes and survival of the cells." (PMID 35221838, 2022). "Owing to its involvement in multiple and varied cellular functions, RAD9A has a dual role in cancer, acting as a tumour suppressor or promoter depending on the tissue." (PMID 35883600, 2022). "Increased levels of RAD9A were correlated with bigger tumours, local recurrence, and higher aggressiveness." (PMID 35883600, 2022). "The TCGA data base collection makes it possible to compare the expression of RAD9A in different tumor entities." (PMID 35221838, 2022). "If RAD9A methylation is relevant for tumor development it should be possible to detect divergent methylation in tumor subclones." (PMID 35221838, 2022). "We propose that RAD9A functions as tumor suppressor in skin fibroblasts and other normal cells of the body and, thus, helps to prevent second cancer." (PMID 21991345, 2011). "This is consistent with the view that RAD9A functions as a tumor suppressor in skin and other tissues by promoting DNA repair in damaged cells and stabilizing the genome before tumorigenesis occurs." (PMID 21991345, 2011). "Interestingly, the Rad9A protein can function as an oncogene or tumor suppressor as both aberrantly high or low Rad9A expression have been linked to breast, lung, thyroid, skin, and prostate tumorigenesis." (PMID 35939452, 2022). "Eight genes (SLC3A2, DARS2, DIP2C, PLOD1, RUNX2, ABCC9, AHNAK, and CLIC3) may be involved in the malignant transformation of tumours, and three genes (CHMP4C, POU5F1, and RAD9A) may have a protective effect in patients with tumours." (PMID 36685927, 2022). "To get a better understanding of the role of the RAD9A gene methylation in the oncogenic transformation we analyzed leukemia cancer samples, tumor cell lines and generated FaDu subclones with divergent methylation values of RAD9A and analyzed its influence on cell viability." (PMID 35221838, 2022). "Increased constitutive and DNA damage-induced levels of RAD9A protein and other genomic caretakers may help to maintain genome stability and prevent second tumor development after radiation and chemotherapy." (PMID 21991345, 2011). "In general, the RAD9A level correlated with tumor size and/or stage." (PMID 21991345, 2011). "The mechanisms by which the multifunctional RAD9A protein acts as an oncogene and a tumor suppressor, respectively are largely unknown." (PMID 21991345, 2011). "Furthermore, we discerned the tumor immune microenvironment with RAD9A expression by CIBERSORT." (PMID 33575255, 2020). "While three genes (AHNAK, ABCC9, and DIP2C) were highly expressed in normal tissues, eight genes (CHMP4C, CLIC3, DARS2, PLOD1, POU5F1, RAD9A, RUNX2, SLC3A2) were highly expressed in tumour tissues." (PMID 36685927, 2022). "Among which, SLC25A15, RAD9A, PRF19, THOC1, and TIPIN were significantly overexpressed in tumor tissues in both the TCGA and our local cohorts." (PMID 36033441, 2022). "Through the HPA database, we found that three genes (ABCC9, AHNAK, and DIP2C) had low expression in patients with tumours, whereas eight genes (PLOD1, SLC3A2, RUNX2, RAD9A, CHMP4C, DARS2, CLIC3, and POU5F1) were highly expressed." (PMID 36685927, 2022). "Nevertheless, it was unexpected that CD8+ T cells and activated NK cells, two players which act in an anti-tumor role in TIME, were positively correlated with RAD9A." (PMID 33575255, 2020).
tumor (continued). "Through the HPA database, we found that three genes, namely ABCC9, AHNAK, and DIP2C, had low expression in patients with tumours, and eight other genes—PLOD1, SLC3A2, RUNX2, RAD9A, CHMP4C, DARS2, CLIC3, and POU5F1—were highly expressed in patients with tumours." (PMID 36685927, 2022). "The current data indicates that both, the lack of or permanent overexpression of RAD9A may have harmful, tumor-promoting effects and the right balance of this important gene is the critical point in tumorigenesis." (PMID 35221838, 2022).
cancer (18 papers, 2007 to 2025). A tumor composed of atypical neoplastic, often pleomorphic cells that invade other tissues. "In general, subclones with RAD9A hypermethylation showed mutations or imbalance in genes crucial for cell stability and cancer, whereas in hypomethylated clones we observed a restoration to normal copy numbers." (PMID 35221838, 2022). "Aberrant RAD9 checkpoint clamp component A (RAD9) expression is associated with various cancers." (PMID 40761744, 2025). "We found a subset of former cancer patients (mostly 1N) with RAD9A mosaic methylation of intron 2, which must be considered as relevant epimutations." (PMID 35221838, 2022). "Recently, RAD9A has been proven to play a vital role in cancer proliferation, metastasis, and drug sensitivity." (PMID 33575255, 2020). "The positive staining areas of RAD9A had a significantly stronger intensity in cancer tissues and were in the higher Gleason scores group." (PMID 33575255, 2020). "Several cancer studies indicate that cells accumulate RAD9A protein during carcinogenesis and also the RAD9A down-regulation by siRNA reduces the tumorogenesis in the cells." (PMID 25244327, 2014). "The cell division check point control protein RAD9A, which is abnormally expressed in several cancer types in animal cells was induced by 138× fold, as compared to the wild type controls." (PMID 25244327, 2014). "We found constitutively decreased levels of RAD9A and several other DNA repair proteins in two-cancer patients, compared to one-cancer patients." (PMID 21991345, 2011). "Because RAD9A protein was most dramatically downregulated in two-cancer patients, we focussed our further study on this cell cycle checkpoint and DNA repair protein." (PMID 21991345, 2011). "The DNA damage checkpoint protein RAD9A was downregulated in both untreated and irradiated somatic cells of two-cancer patients, compared to one-cancer patients." (PMID 21991345, 2011). "Nevertheless, our results suggest that the constitutive RAD9A protein levels as well as the extent of induction after DNA damage vary between two-cancer and one-childhood cancer patients." (PMID 21991345, 2011). "Quantification of mRNA expression by real-time RT PCR revealed lower RAD9A mRNA levels in both untreated and 1 Gy γ-irradiated cells of two-cancer patients." (PMID 21991345, 2011). "In the one-cancer group, RAD9A was overexpressed more than twofold at 1 h and 4 h after irradiation, compared to the constitutive protein level." (PMID 21991345, 2011). "Analysis of various normal cell types in larger patient populations, for example adult cancer survivors are necessary to support a role for RAD9A in DNA damage-induced carcinogenesis." (PMID 21991345, 2011). "The RAD9A protein level increased in response to DNA damage, however to a lesser extent in the two-cancer patients." (PMID 21991345, 2011). "We did not detect suspicious mutations in RAD9A or other cancer susceptibility genes, in our patient collective." (PMID 35221838, 2022). "Due to the dual role of RAD9A in cancer, we would assume the hypermethylation in RAD9A, seen in the five patients in mosaic, as potentially harmful, because it may activate RAD9A transcription." (PMID 35221838, 2022). "Therefore, larger prospective studies in various cancer types and tissues are needed to generally correlate RAD9A epimutations with cancer incidence and therapy outcomes." (PMID 35221838, 2022). "RAD9A belongs to a growing group of genes with dual roles in cancer." (PMID 21991345, 2011). "Three matched pairs represent outliers or extreme outliers in the box plot diagrams, indicating that relative RAD9A expression levels can considerably vary between patients and are not always reduced in two-cancer patients." (PMID 21991345, 2011). "The constitutive RAD9A mRNA levels (without induction of DNA damage) were significantly lower in two-cancer patients (−2.40x, p = 0.004), compared to one-cancer patients." (PMID 21991345, 2011).
infection (2 papers, 2009 to 2022). The state of being infected such as from the introduction of a foreign agent such as serum, vaccine, antigenic substance or organism. "Most importantly, there was a 138-fold increase in RNA accumulation of the cell division checkpoint control protein RAD9A, suggesting its involvement in the TMV infection process." (PMID 36426154, 2022).
RAD9A also shares sentences with these, for which no sentence is quoted: lung cancer (5 papers); non-small cell lung carcinoma (2); prostate (2); skin tumor (2); autoimmune thyroid disease (1); breast tumor (1); cataract (1); colon cancer (1); gastric cancer (1); glioma (1); head and neck cancer (1); influenza (1); prostate tumor (1); squamous cell carcinoma (1); Telangiectasia (1).